IL6 (interleukin 6)
Diseases named in the same sentence as IL6 in open-access papers (continued):
Sharing a sentence is not in itself a finding about the gene and the disease.
tumor (continued). "It is worth to point out that IL-6 is a cytokine important in angiogenesis and tumor progression, and its levels are increased in both blood and saliva of patients diagnosed with HNSCC." (PMID 29854027, 2018). "When we grouped samples according to their distinct IHC scores by tumor differentiation and metastasis status, those with poor differentiation or metastasis harbored higher ERβ/IL6 expression." (PMID 29970138, 2018). "The impact of the TLR4-mediated pathway to control the production of IL-6 and IL-8 has been shown and that after release into the tumor microenvironment, it can have a paracrine effect on either the neighboring cancer cells to survive or resist to PTX." (PMID 29486738, 2018). "Astrocytes also contribute to tumor migration and invasion by release IL-8 or IL-6 which promotes expression of VEGF in tumor cells." (PMID 30567306, 2018). "Recently, it has also been reported that IL-6 is an important mediator of the tumor-promoting effect of inflammation-related diseases, and that patients with advanced or metastatic colon cancer have elevated serum IL-6 levels." (PMID 30308035, 2018). "In the case of IL-6, circulating levels remained all but undetectable in patients displaying tumor response throughout the entire follow-up period, with a baseline median of IL-6: 0 (IQR, 2.22) vs. 4.5 pg/mL (IQR, 5.1), p-value=0.072." (PMID 30651923, 2018). "The results of this study suggest that the expression of MMPs in tumor cells is regulated by cell density through the synergistic paracrine mechanism of IL-6 and IL-8 via the JAK2/STAT3 signaling pathway." (PMID 30220965, 2018). "MACinflam produced in cultures containing IL-6 plus TNFα or IFNγ also mediated significant tumor cell lysis." (PMID 29632539, 2018). "In summary, our study identifies a vascular niche for the regulation of tumor immunity and reveals an IL-6-mediated mechanism controlling macrophage alternative activation and GBM progression." (PMID 29422647, 2018). "Chemotherapy also induces cancer cells to secrete more inflammatory IL-6 and prostaglandin E2, which drives monocyte differentiation toward tumor-promoting macrophages." (PMID 30619850, 2018). "Together, it is possible that MDSCs promote tumor growth, and aggressiveness is mediated primarily though IL-6." (PMID 30405034, 2018). "The excessive production of proinflammatory cytokines such as IL1 and IL6, growth factors, chemokines, and proteases by macrophages results in precancerous lesions, tumor growth promotion, and metastasis." (PMID 30060484, 2018). "SASP factors such as IFNγ and IL-6 skew macrophage polarization toward the anti-tumor M1 macrophages." (PMID 29868482, 2018). "IL-6 levels in the tumor control group were significantly (p < 0.05) upregulated to 293 ± 9 pg/mL when compared with levels in the blank control group (135 ± 3 pg/mL)." (PMID 29794990, 2018). "Our model is unique in that it includes the molecular level details IL-6 signal initiation and its effect on tumor cell survival and proliferation, while also capturing the influence of IL-6 on the probability of self-renewal for cancer stem cells." (PMID 29351275, 2018). "Recent evidence shows that IL-6R is overexpressed on CSCs and IL-6 secreted by both tumor cells and endothelial cells (ECs) enhances the survival, self-renewal and tumor initiation potential of cancer stem cells in HNSCC." (PMID 29351275, 2018). "The paired samples t-test shows that ERβ/IL6 expression in metastatic lymph nodes was significantly higher than that in primary tumor tissue (p < 0.001)." (PMID 29970138, 2018). "All these findings suggested that tumor-derived IL-6 was the critical factor that blocked myeloid differentiation and the development of e-MDSCs." (PMID 30083161, 2018).
tumor (continued). "Stimuli from proinflammatory cytokine IL-6 expressed by tumor cells, is sufficient to induce the expression of Twist1 in normal fibroblasts and transdifferentiate them into CAFs through the activation of STAT3 pathway." (PMID 30175384, 2018). "In EBV+ HL, receptors for IL-3, IL-6, IL-7, IL-9, IL-13, IL-15, and IL-21 are present on the tumor cells." (PMID 29652813, 2018). "Consistent with earlier findings, R848-treated mMDSCs lysed tumor targets as did cells cultured with IFNγ or the combination of IL-6 plus TNFα." (PMID 29632539, 2018). "Detailed histological analysis showed that 26/28 (93%) Δ122/Δ122 IL-6+/+ mice, 8/9 (89%) of Δ122/Δ122 IL-6+/− mice and 14/20 (70%) Δ122/Δ122 IL-6−/− mice had developed malignant tumours at the time of death." (PMID 29343721, 2018). "In esophageal squamous cell carcinoma, CXCR7 expression is upregulated in tumor cells through STAT3/NF-kB signaling stimulated by CAF-derived IL-6, ultimately promoting resistance against cisplatin and 5-fluorouracil." (PMID 30356656, 2018). "In four different mouse tumor models, trabectedin significantly inhibited the production of cytokines including CCL2 and IL6, which are important in promoting tumor growth." (PMID 29594035, 2018). "Human bone marrow-derived MSCs can differentiate into CAFs, which produce soluble pro-tumorigenic factors such as interleukin 6 (IL-6) to enhance tumor growth in an EOC xenograft model." (PMID 28929459, 2018). "We treated SW620 cells with interleukin-6 (IL-6) in vitro to mimic the paracrine inflammatory microenvironment of tumor cells." (PMID 30363706, 2018). "A balance between Treg and Th17 is essential for maintaining anti-tumour immunity, and IL-6 plays a pivotal role in regulating this balance." (PMID 32185304, 2018). "DCs are ex vivo loaded with tumor-specific antigens and are matured under the influence of danger signals such as tumor necrosis factor-α, IL-1β and IL-6 or TLR ligands." (PMID 30235890, 2018). "This study reveals a new strategy to decrease MMP expression through pharmacological intervention of the cognate receptors of IL-6 and IL-8 to decrease metastatic capacity of tumor cells." (PMID 30220965, 2018). "In general, effector cells rejected the tumor cells, accompanying with cytokine release, including IL-2, TNFα, IL-6, and IFNγ." (PMID 30103775, 2018). "On the other hand, MSCs promoted cancer in progressive stages due to the elevation of proinflammatory cytokines (IFNγ, TNFα, IL6 and IL1β) expression in the tumor microenvironment." (PMID 30346985, 2018). "IL-6 and IL-8 both represent immunomodulatory cytokines, which have previously been described as pro-malignant mediators in different tumor entities." (PMID 29899223, 2018). "Activation of TLR4 in tumor cells promotes the synthesis of NFκB target genes, including IL-6 and IL1β, which results in resistance of tumor cells against cytotoxic lymphocytes." (PMID 29679017, 2018). "These early studies were of relevance as they began to unveil the role of IL-6 dependence in MM growth and the importance of tumor microenvironment in promoting MM development in vivo." (PMID 29732008, 2018). "Pro-inflammatory cytokines such as IL-6, IL-1β and TNF are produced by a variety of cell types in a cancer including the tumor cells themselves, cancer-associated fibroblasts, and tumor-associated macrophages." (PMID 29883385, 2018). "At the same time, IL6 has an antitumor effect, which can directly or indirectly enhance the tumor-cytotoxic effect of the natural killer cell and cytotoxic lymphocytes." (PMID 30671125, 2018). "Our results showed that adipocyte-derived IL-6 and leptin stimulate the migration of tumor cells via upregulation of PLOD2 expression." (PMID 30563531, 2018). "In a gefitinib-resistant NSCLC model, HHT induced anti-tumor effects by suppressing interleukin-6 (IL-6)/JAK1/STAT3 signaling." (PMID 29844447, 2018).
tumor (continued). "Once in contact with tumour cells, BM‐MSCs enhance the levels of GRO‐α, MCP‐1, interleukin (IL)‐6 and IL‐8 in the tumour microenvironment." (PMID 29517849, 2018). "IL-6 positively affects tumor development and is recognized as a key regulator of immunosuppression in advanced cancer." (PMID 30587810, 2018). "A recent report demonstrated that PDT-generated tumor cell lysate induces IL-1α, IL-1β, and IL-6 secretion from DCs suggesting that PDT-induced immune enhancement is due to DCs activation." (PMID 30680248, 2018). "Genetic inactivation of Il6 signaling in a mouse model of BCC significantly reduced in vivo tumor growth by interfering with HH/GLI‐driven BCC proliferation." (PMID 29987839, 2018). "In conclusion, our data suggest that cancer-derived exosomal gp130 plays a critical role in the tumor environment via activation of the IL-6/STAT3 pathway in macrophages." (PMID 29867925, 2018). "When comparing IL6 IHC scores between primary tumor and metastatic lymph nodes, we see a rising trend." (PMID 29970138, 2018). "PPARγ and RXR agonists were demonstrated to inhibit interleukin-6 (IL-6) promoter activity and reduce MMP-2 and MMP-9 expression and activity in tumor-associated fibroblasts." (PMID 29599799, 2018). "Previous studies have shown IL-6 is expressed in tumor epithelial cells resulting in tumor cell growth." (PMID 30458886, 2018). "mTORC1 involvement in tumour cachexia was evidenced in ApcMin/+ mice, a model of colorectal cancer that develops cachexia that is dependent on interleukin-6." (PMID 30061533, 2018). "Among the growth factors and cytokines secreted by MDSCs, interleukin-6 (IL-6) is the central tumor growth factor in vitro and in vivo in MM, and has been verified to be a prognostic factor for MM." (PMID 30405034, 2018). "We previously reported that IL-6 is crucial for aggressive tumor growth, MDSC recruitment, and a poor radiation response." (PMID 30587810, 2018). "Lastly, IL6 evaluated in our study was previously related to an advanced stage of CRC development where it was proved that IL6 promoted tumor cell proliferation and inhibited apoptosis through gp130 activation." (PMID 30326660, 2018). "The reduction in tumour incidence between Δ122/Δ122 IL-6+/+ and Δ122/Δ122 IL-6−/− mice was significant (p = 0.036, χ2-test)." (PMID 29343721, 2018). "Elevated serum and tissue levels of IL-6 and IL-8 are markers of poor clinical outcome in breast cancer and, along with CXCL1, both IL-6 and IL-8 have been implicated in TNBC tumor progression in vivo." (PMID 30111846, 2018). "In response to iC3b-positive tumor cells, β-glucan-primed leukocytes produced cytokines including TNF-α, IFN-γ, IFN-α, and IL-6, which are associated with tumor cell destruction." (PMID 29535722, 2018). "To investigate the in vivo therapeutic efficacy of IL-6 NAb in tumors, we measured tumor volumes using US imaging." (PMID 30134951, 2018). "But long-term IL-6 stimulation in local tumor microenvironment executed significant inhibitory effect on SOCS3 in myeloid cells and thus induced sustained activation of the JAK/STAT pathway." (PMID 30083161, 2018). "Tumor pDC produced low quantities of IL-6, TNF-α, IFN-α, macrophage inflammatory protein-1β (MIP-1β), and RANTES (CCL5) in response to TLR stimulation, in contrast to pDC from ascites or peripheral blood." (PMID 30200478, 2018). "Pro-inflammatory cytokines, such as TNF-α, IL-1β, and IL-6, contribute to the induction of tumor development by enhancing cancer stemness." (PMID 30486830, 2018). "The concentration of IL6 in tumor tissue correlates with tumor progression and overall survival in patients with NSCLC, and higher postoperative serum IL-6 levels predict a higher risk of early postoperative recurrence." (PMID 29970138, 2018).
tumor (continued). "Gradients of stromal-derived factor-1 (SDF-1) increase the migratory capacity of tumor cells and provide directionality, whereas cytokines, such as interleukin-6 (IL-6), modulate the proliferation and therapy response characteristics of tumors." (PMID 29732370, 2018). "Collectively, our findings support the notion that G3BP1 promotes tumor progression and metastasis through IL-6/G3BP1/STAT3 signaling axis in RCC." (PMID 29717134, 2018). "IL-6 promotes tumour progression by regulating survival, apoptosis, proliferation, angiogenesis, and invasiveness of cancer cells." (PMID 30310111, 2018). "IL-6 also supports tumor cell survival by inducing the expression of survivin through direct binding of STAT-3 to the survivin promoter." (PMID 29930760, 2018). "We have developed a preliminary mathematical model of this experimental paradigm and our early results show high fractional occupancies of IL-6R lead to even greater interdependencies among IL-6, tumor growth dynamics and the tumorigenic potential of CSCs." (PMID 29351275, 2018). "In our two complementary in vivo models, IL6‐neutralising therapies paradoxically increased the incidence of metastasis despite sensitisation of primary tumours of ADT." (PMID 29540470, 2018). "IGF-1R inhibition in tumor epithelial cells elevated interleukin (IL)-6 and C-C motif chemokine ligand 2 (CCL2) expression, which was reversed by ROS scavenging." (PMID 30458886, 2018). "The model includes the effects of human tumor cell-secreted IL-6 signaling on tumor cell survival and proliferation, and also captures the effect of IL-6 on the probability of self-renewal for cancer stem cells." (PMID 29351275, 2018). "IL-6 modifies the tumor microenvironment and promotes breast and lung cancer development and progression." (PMID 29601548, 2018). "IL-6 is a pleiotropic cytokine that is involved in tumor growth, invasion and metastasis in malignancies." (PMID 29416638, 2018). "A further mechanistic study showed that tumor cell-intrinsic Tim-3 would promote HCC development by triggering auto-secretion of IL-6 and then accelerating tumor growth through the STAT3 signaling pathway." (PMID 30309387, 2018). "Upregulation of Tim-3 on macrophages facilitates their M2 polarization and increases IL-6 secretion, further promoting tumor growth." (PMID 30309387, 2018). "In particular, Jagged1 is a ligand of Notch, one of the most important downstream mediators of the pro-metastatic TGF-β, that directly activates OC differentiation and promotes tumor growth, stimulating IL-6 production by OBs." (PMID 29461491, 2018). "Using HCC cell-line analysis, we showed the inhibitory actions of STC1 on the pro-migratory effects of IL-6/IL-8, the growth of tumor spheroids in culture and the development of tumor mass in nude mice model." (PMID 29467934, 2018). "As previously shown here, AIRE is significantly regulating IL-6 expression so we investigated the influence of AIRE on monocyte differentiation in tumor microenvironment." (PMID 29795364, 2018). "IL-6-exposed macrophages (M(IL-6)) strongly enhanced transendothelial migration of tumour cells, which was HO-1 dependent as SnMP completely abrogated this effect." (PMID 30054470, 2018). "Briefly, dCAR-T cells in mice bearing the cognate tumor cells (AsPC-1) released high levels of cytokines, including 2320 pg/mL IL-2, 609 pg/mL TNFα, 2486 ng/mL IL-6, and 67 ng/mL IFNγ, which was similar to that observed for cytotoxicity." (PMID 30103775, 2018). "PPARγ repression in pancreatic cancer cells results in the constitutive production of pro-inflammatory cytokines, including TNFα, IL-6, and IL-1β, relevant in the recruitment of macrophages and neutrophils into the tumor site." (PMID 30154786, 2018). "In line, recent CAC studies in mice demonstrate that enriching high-fat diets with TNF- and IL-6-inhibiting supplements leads to the reduction of inflammation and mucosal injury in the colons of mice and ultimately to less tumor development." (PMID 30591653, 2018).
tumor (continued). "Increased levels of IL-6 have been reported in various pathological conditions, such as infection (bacteria and virus), immune disease, inflammation, and tumours." (PMID 29984230, 2018). "This is noteworthy as Rorgt+ T cells are programmed by milieu influences of TGFbeta and IL-6, key cytokines known to be enhanced during involution and generally considered suppressive of anti-tumor immunity." (PMID 30285905, 2018). "Firstly, we profiled the transcript levels of major tumor microenvironment cytokines IL-6, IL-10, tumor necrosis factor-α (TNF-α), and transforming growth factor-β (TGF-β) in PC3 cells in both conditions: with ectopically expressed AIRE and AIRE knockdown." (PMID 29795364, 2018). "In agreement with sustained STAT3 activation observed in breast cancer, unchecked cell division, resistance to cell apoptosis, as well as tumor growth in mice result from IL-6/STAT3 activation in mammary CSCs." (PMID 30081496, 2018). "The IL-6 expressed by tumor cells stimulates the expression of RANKL and increases tumor cell sensitivity to its effects." (PMID 30180883, 2018). "There is little information available about the in vitro effect of IL-6 and IL-10 on the phenotypic behaviour of BC cells in terms of tumour cell migration or adhesion to lymphatic and blood endothelium, which are key steps in the metastatic process." (PMID 29256156, 2018). "Here, we cultured bone marrow cells with IL-6 and GM-CSF in vitro to generate a population of bone marrow MDSCs (BM-MDSCs) similar to G-MDSCs from tumor-bearing mice in regards to phenotype, morphology and suppressive-function." (PMID 29677215, 2018). "Our previous study showed that MSCs in the bone microenvironment promoted OS progression and protected tumor cells from drug-induced apoptosis through IL-6/STAT3 signaling." (PMID 29915309, 2018). "During the malignant progress of tumors, tumor-related inflammatory cells are activated and secret several pro-inflammatory cytokines, including tumor necrosis factor, IL-1, IL-6, and IL-8." (PMID 29568406, 2018). "This multi-centre, randomised clinical trial was specifically designed to address the question of the potential effects of surgically induced inflammation on perioperative tumor kinetics using IL-6 as a surrogate marker." (PMID 30081854, 2018). "Blocking IL-6 signaling by the intravenous injection of IL-6 neutralizing antibody resulted in suppressed tumor growth compared with that of the controls, which was monitored in vivo with US imaging." (PMID 30134951, 2018). "Mesenchymal stem cell derived CAFs recruited to the stroma of the dysplastic stomach express IL-6, Wnt5a, and bone morphogenetic protein 4, which promote tumor growth through DNA hypomethylation." (PMID 30380628, 2018). "STAT3 constitutive activation has been shown to contribute to tumor development and progression, while IL-6/JAK pathway plays a crucial role in aberrant STAT3 signaling cascades." (PMID 29443735, 2018). "IL-6 in the tumor microenvironment has been demonstrated to be a potent driver of tumor cell growth." (PMID 29867053, 2018). "Previous studies looking at expression of IL-6 and IL-10 showed similar cytoplasmic expression patterns in tumour cells of the breast and other tumour types." (PMID 29256156, 2018). "Specifically, inhibition of estrogen signaling was accompanied by reformatting the TME toward a pro-tumor phenotype evidenced by upregulated expression of Il6, Tgfb, and Il17 among other pro-tumor immune markers." (PMID 30389925, 2018). "Along with tumour progression, there was a gradual increase in plasma IL-6 concentration in tumour-bearing mice." (PMID 29788918, 2018). "On the other hand IL-6 secretion from the tumor leads to its positive feedback and to the continuous secretion of PEc." (PMID 30134795, 2018). "The metastatic subline HT-L1 expressed higher levels of IL-6 and IL-10 than the primary tumor subline HT-S1." (PMID 30209389, 2018).